SIRT6 (sirtuin 6)
Diseases named in the same sentence as SIRT6 in open-access papers (continued):
Sharing a sentence is not in itself a finding about the gene and the disease.
cancer (218 papers, 2011 to 2026). A tumor composed of atypical neoplastic, often pleomorphic cells that invade other tissues. "Longevity in centenarian Ashkenazi Jews was recently associated to novel allelic variants of SIRT6 (N308K/A313S), which ameliorate genome maintenance and DNA repair, and suppress cancer cells." (PMID 41827746, 2026). "Dysregulation of SIRT6 is believed to be associated with aging and cancer, making it of pharmacological interest." (PMID 40147774, 2025). "SIRT6 dysregulation is associated with many diseases, including cancer, cardiovascular disease (CVD), neurodegenerative diseases, and diabetes." (PMID 40563894, 2025). "In view of the established role of metabolic reprogramming as a cancer hallmark, targeting the SIRT6 axis offers a promising strategy for modulating energy homeostasis in both malignant and metabolic diseases." (PMID 41463311, 2025). "The molecular mechanisms underlying SIRT6 effects on longevity or on the two contradictory roles in cancer development are not well understood, limiting the search for medically useful drugs that target the enzyme." (PMID 38415718, 2024). "Loss-of-function assays reveal that SIRT6 promotes cell proliferation, migration, and invasion, with silencing SIRT6 significantly impairing these critical cancer processes." (PMID 39796040, 2024). "SIRT6 plays pivotal roles in cancer-associated pathways, such as maintaining genomic stability, inhibiting cell proliferation, and regulating energy metabolism." (PMID 38891773, 2024). "This study focused on ROS-mediated cancer cell death because ROS are associated with a variety of cellular processes involving both Sirt1 and Sirt6." (PMID 38254877, 2024). "SIRT6 is implicated in cancer progression and onset from dual-sided effects since both blocking and inducing apoptosis result in opposite outcomes." (PMID 37763801, 2023). "High nuclear levels of SIRT6 promot cancer development and is significantly associated with poor overall survival." (PMID 35463332, 2022). "Recent studies have underlined the role of SIRT6 in the development of several types of cancer, such as breast cancer, liver cancer, pancreatic cancer, and colon adenocarcinoma." (PMID 35745656, 2022). "Conversely, Sirt6‐deficient mice exhibit accelerated functional decay, shortened lifespans, and progeroid syndrome as well as ageing, cancer and metabolic disorders." (PMID 35842903, 2022). "It established a significant association between SIRT6 expression and a decline in cancer patients’ OS (HR = 0.66, 95% CI = 0.45–0.97, P < 0.001) and DFS (HR = 0.48, 95% CI = 0.26–0.91)." (PMID 35172823, 2022). "Previous reports have shown that Sirt6 deficiency has linked to many diseases, such as cancer, neurodegeneration and aging." (PMID 33869219, 2021). "It is noteworthy to mention that overexpression of SIRT6 is associated with the induction of apoptosis in cancer cells." (PMID 33920726, 2021). "SIRT6-deficient mice have shortened lifespan, defects in DNA repair and a high incidence of cancer due to oncogene activation." (PMID 33567774, 2021). "In cancer-associated pathways, ROS are crucial for modulating Sirt6 to inhibit cell survival and promote cell death." (PMID 33727672, 2021). "The magnitude of acetyl-CoA changes that we observe in SIRT6 deficient cancer cells is comparable to those previously shown to have functional effects on histone acetylation and on cellular differentiation phenotypes." (PMID 34573442, 2021). "SIRT6-deficient mice show shortened lifespan, defects in DNA repair and have a high incidence of cancer due to oncogene activation." (PMID 33567774, 2021). "The reduction of SIRT6 expression is linked to the progression of different types of cancers such as colorectal, breast, ovarian, hepatocellular, and lung cancers." (PMID 33920726, 2021).
cancer (continued). "In this follow‐up study, we demonstrate that muscle‐specific SIRT6 over‐expression impedes cancer‐associated muscle atrophy by targeting different pathways, including autocrine and paracrine signalling." (PMID 34212132, 2021). "Especially, increased invasiveness of SIRT6-overexpressing cancer cells was associated with activation of the ERK1/2-MMP9 pathway and secretion of IL8 and TNF cytokines." (PMID 33198792, 2020). "The results of this study demonstrated that Galloflavin and Ellagic acid affected SIRT6 activity and the expression of proteins that are associated with cancer development." (PMID 32905943, 2020). "SIRT6 is also associated with autophagy in bronchial epithelial cells and the Warburg effect in cancer cells." (PMID 32983963, 2020). "SIRT6 activation inhibits this glycolytic shift, and thus SIRT6 deficiency increases cell survival, growth and proliferation in many cancers." (PMID 32905943, 2020). "The nuclear protein SIRT6 exerts diverse cancer-associated functions by controlling energy metabolism and stress resistance." (PMID 32488123, 2020). "This evidence shows SIRT6 regulatory activity, linking energy homeostasis to lifespan, and shows that aging is presented as one of the major risk factors of cancer." (PMID 31591350, 2019). "Although multiple studies has elucidated that SIRT6 is involved in the aging-associated pathologies including metabolic disease and cancer, we firstly explored and announced the potential role of SIRT6 in virus replication." (PMID 31708789, 2019). "Further, SIRT6 deficiency is linked to increased ribosome biogenesis in cancer cells driven by the de-repression of the MYC transcription factor." (PMID 31372634, 2019). "Down-regulation of SIRT6 expression is associated with higher cancer staging and grades, as well as poor survival rates in cancer patients." (PMID 31128573, 2019). "SIRT6 deficient mice were three times more likely to relapse in cancer progression when compared to mice that showed high levels of SIRT6." (PMID 29966233, 2018). "Sirt6 which is implicated in the control of aging, cancer, and metabolism, has been shown to have anti-fibrosis function in heart and liver." (PMID 28977842, 2017). "In contrast, many SIRT6 biological functions are associated with anti-cancer effects, including its role in cancer cell apoptosis, enhancing sensitivity to radiation damage and reducing cell viability." (PMID 27777384, 2016). "Recently, SIRT6 was implicated in cancers, although the role of SIRT6 in various cell types is different." (PMID 27777384, 2016). "Recent studies evaluated that SIRT6 deficiency is associated with various diseases including inflammation and different types of cancer." (PMID 26437418, 2015). "Notably, many of the molecular deficiencies that characterize SIRT6-knockout and -knockdown cells are also characteristic of cancer cells." (PMID 39955062, 2025). "Nevertheless, SIRT6 in our study was investigated as a factor causing cancer metastasis." (PMID 35840633, 2022). "However, despite these reports, there are also reports that the higher expression of SIRT6 is closely associated with shorter survival in cancer patients, and SIRT6 is involved in the stimulation of molecules closely associated with cancer progression." (PMID 34359939, 2021). "This study was undertaken to test whether muscle‐specific over‐expression of SIRT6 can block the cancer‐associated muscle wasting in vivo and to identify additional relevant targets of SIRT6, which can explain its ability to maintain muscle health." (PMID 34212132, 2021). "Inhibition of ACLY in SIRT6-deficient cells reversed the dysregulated expression and histone hyperacetylation and prevented the migration and adhesion phenotypes of SIRT6-deficient cancer cells." (PMID 34573442, 2021).
cancer (continued). "Galloflavin and Ellagic acid have also shown anti-cancer potential in colon cancer cell lines, therefore we used Caco2 cell line to evaluate their effects on the proliferation and expression levels of SIRT6 and SIRT6 associated proteins involved in cancer development." (PMID 32905943, 2020). "Interestingly, mutations in D63 had previously been reported to provoke the loss of SIRT6 function in cancer, and have recently been shown to be lethal in humans." (PMID 31995034, 2020). "Moreover, a SIRT6 K33R hypoacetylation mimic can rescue DNA repair defects in SIRT1-deficient cancer cells." (PMID 33117804, 2020). "Because SIRT6 has been implicated in longevity, metabolism, DNA-repair, and inflammatory response reduction, it is an interesting target in inflammatory and metabolic diseases as well as in cancer." (PMID 29515203, 2018). "SIRT6 point mutation was reported to occur in several types of cancers." (PMID 27824900, 2016). "Future studies are needed to address these possibilities and investigate whether oxidative stress is involved in loss of Sirt6 expression and function in cancer, cardiomyocyte hypotrophy, and inflammation." (PMID 25162034, 2014). "However, SIRT6 has been implicated as a therapeutic target in diverse conditions such as cardiovascular, Alzheimer’s, cancer, and several other age-related diseases." (PMID 34867200, 2021). "Also, Sociali’ group showed that SIRT6 inhibitors Quinazolinedione could enhance cancer cells susceptibility to chemotherapeutic agents." (PMID 29563873, 2018). "SIRT6 activation protects against metabolic diseases and aging, and its inhibition is considered a therapy against cancer and inflammation." (PMID 41361972, 2026). "Flavonoids are among the molecules recognized as activators of SIRT6, and they show potential for treating metabolic, inflammatory, and anti‐cancer disorders." (PMID 41361972, 2026). "Within this landscape, the SIRT6 protein emerges as a focal point of interest owing to its pivotal role in regulating metabolic processes, cancer progression, and aging mechanisms." (PMID 41361972, 2026). "SIRT6 is a histone deacetylase that plays a role in genomic stability, DNA repair, cancer, metabolism, and aging." (PMID 41563000, 2026). "As in the present study, we previously examined Sirt6 mRNA expression levels in several cancer cell lines (A2780, HeLa, Huh7, MBA-MD-231, SMMC-7721 and SW480) with UBCS039 treatment and compared the expression level with corresponding normal cells." (PMID 41530841, 2026). "Activation of SIRT6 protects against metabolic and aging‐related diseases, and its inhibition is considered a therapy against cancer and inflammation." (PMID 41361972, 2026). "SIRT6 is a fundamental sirtuin that governs several disease processes encompassing inflammation and cancer, including HCC." (PMID 41827746, 2026). "In conclusion, pharmacological activation of SIRT6 can effectively reverse cancer cachexia‐related lipolysis, presenting a promising mechanism and drug candidate to reduce cancer‐associated mortality." (PMID 39971710, 2025). "Conversely, SIRT6 inhibitors, including SIRT6-IN-3 and SIRT6-IN-4, have been reported to induce apoptosis in cancer cell lines." (PMID 40705152, 2025). "This bimodal effect, in which SIRT6 protects normal tissues while sensitizing cancer cells, again points to its candidate status as a context-dependent metabolic regulator." (PMID 41425553, 2025). "This was consistent with that the lipid droplets were smaller in WAT of WT + LLC mice compared with TG + LLC mice, illustrating that SIRT6 overexpression can decrease cancer‐induced WAT browning and lipolysis in vivo." (PMID 39971710, 2025). "In humans, rare centenarian SIRT6 variants (N308K/A313S) exhibit enhanced interaction with Lamin A, increased mono-ADP-ribosyltransferase activity, stronger retrotransposon suppression, and improved cancer cell killing compared with wild-type SIRT6." (PMID 41463311, 2025).
cancer (continued). "Inactivation of sirtuin 6 in cancer cells leads to the accumulation of nuclear ACLY protein, increasing nuclear acetyl-CoA pools and driving locus-specific histone acetylation." (PMID 40710366, 2025). "Cisplatin and doxorubicin are FDA‐approved chemotherapeutic drugs, and we have found a protective benefit of SIRT6 against side effects of commonly used cancer treatments." (PMID 39971710, 2025). "Altogether, our findings join many others in providing a case for SIRT6 activators and agonists as multi‐faceted strategies in the prevention and treatment of cancer cachexia." (PMID 39971710, 2025). "SIRT6, a molecule that is important in DNA repair and has an anti-oncogenic effect in most cancers, appears to be sneaky in AML and can work in favor of the disease." (PMID 40149343, 2025). "In this study, we identify a novel role for SIRT6 in the treatment of cancer, describing its benefit in ameliorating cancer‐induced cachexia and providing further rationale for investigation of SIRT6 activators in cancer treatment protocols." (PMID 39971710, 2025). "In pre-clinical settings, SIRT6 inhibitors exhibit anti-inflammatory and anti-cancer effects and improve glucose tolerance." (PMID 40806744, 2025). "SIRT6 can act as a tumor promoter or suppressor, and its expression is downregulated in some cancers, including hepatocellular carcinoma, colorectal cancer, and head and neck squamous cell carcinoma, and is associated with the inhibition of apoptosis." (PMID 39940397, 2025). "SIRT6 also modulates histone acetylation states, influencing chromatin structure and gene expression, particularly in cancer biology." (PMID 40710366, 2025). "SIRT6 also suppresses cancer proliferation in NSCLC, PDAC, glioma, endometrial carcinoma, and melanoma via inhibition of multiple pathways." (PMID 39215785, 2025). "Currently, SIRT6 has been identified as a key factor in the onset and progression of cancer and CVD." (PMID 40563894, 2025). "Through these methods, researchers can gain deeper insights into the allosteric regulation of SIRT6 and facilitate the rational design of novel modulators for cancer therapy." (PMID 39981029, 2025). "Reduced SIRT6 expression has been observed in various human cancers, and its expression level has been positively correlated with the prognosis of cancer patients." (PMID 38891773, 2024). "Considering that UHRF1 is an epigenetic modifier aberrantly overexpressed in many cancers, we intended to focus on the relationships between SIRT6 and UHRF1." (PMID 39709438, 2024). "Validation in TCGA datasets revealed significant correlations between LRP1, FASN, SIRT6, and clinical outcomes in BC patients, suggesting their potential as cancer biomarkers." (PMID 39071712, 2024). "The transcription factor AP-1 component c-Jun promoted cell survival during cancer initiation by inhibiting c-Fos-induced Sirt6 expression." (PMID 38332150, 2024). "While other sirtuins, such as SIRT1 and SIRT6, exhibit a similar dual role in cancer, SIRT7 stands out due to distinctive attributes that sharply distinguish it from other family members." (PMID 38383727, 2024). "SIRT6 influences glycolysis and glucose metabolism and is a Myc co-repressor, indicating a potential role in the metabolic activity of cancer cells." (PMID 39366656, 2024). "Previous study showed that SIRT6 suppressed the NF‐κB activation, and markedly impairs the initiation and development of cancer cells." (PMID 37936548, 2024). "Cellular activity of UBCS039 was demonstrated by decreased H3K9 acetylation and Sirt6-mediated increases in autophagosome formation and autophagy-induced cell death in several cancer cell lines." (PMID 38474697, 2024). "Validation in TCGA datasets highlighted the prognostic significance of LRP1, FASN, and SIRT6, suggesting their potential as cancer biomarkers." (PMID 39071712, 2024).
cancer (continued). "In accordance with previous study, we found that the inflammatory factors including ac‐NF‐κB, NF‐κB, and TNF‐α were increased in SIRT6 KO mice, which are important proteins that promotes cancer cell proliferation." (PMID 37936548, 2024). "SIRT6 is increasingly recognized for its pivotal role in cancer biology, particularly given its multifaceted involvement in regulating cellular metabolism, maintaining genomic stability and modulating inflammatory responses." (PMID 39682281, 2024). "The anti-tumorigenic activity of Sirt6 is mediated by anti-apoptotic factors influencing cancer cell survival and development." (PMID 38254877, 2024). "For example, resistance to programmed cell death and DNA damage are important contributors to SIRT6 cancer promotion." (PMID 39479446, 2024). "Evidence suggests that SIRT6 can modulate the expression of pro- and anti-apoptotic factors, thereby influencing cancer cell survival in a context-dependent manner." (PMID 39682281, 2024). "The dysregulated expression observed in various cancers positions SIRT6, LRP1, and FASN as potential candidates for cancer biomarkers." (PMID 39071712, 2024). "Nevertheless, SIRT6 has also been reported to promote cancer progression in skin cancer, prostate cancer, and breast cancer." (PMID 38891773, 2024). "We further assessed the protein expression of SIRT6 in cancer tissues and paired normal tissues in a cohort of 75 cases of CRC patients." (PMID 38891773, 2024). "The in vivo efficacy of the MDL compound family and Compound 12q demonstrate that selective Sirt6 activation has therapeutic potential in multiple types of cancer and neurological damage." (PMID 38474697, 2024). "The high expression of SIRT6 was correlated with the location of cancer tissue and Broder staging in CSCC patients." (PMID 38548549, 2024). "Invasion and migration are critical features of malignant tumors, and SIRT6 silencing significantly reduced the proliferation, migration, and invasion of CSCC cells, providing evidence for the role of SIRT6 in CSCC cell growth and motility." (PMID 38548549, 2024). "The distinct mechanism of action conferred by allosteric modulation paves the way for the development of therapeutics that can precisely navigate the complexities of SIRT6’s role in cancer progression." (PMID 39682281, 2024). "In parallel, related to cancer metabolism, we observed SIRT6 downregulation and c-Myc upregulation in PEO-4 cells." (PMID 39349928, 2024). "SIRT6 also plays important roles in multiple diseases, including metabolic diseases, aging and cancer." (PMID 37542062, 2023). "SIRT6 has been reported to play a prominent role in promoting cancer cell survival under oxidative stress, confirming its role in redox-related cellular homeostasis." (PMID 38235110, 2023). "The inhibition of SIRT6 activity with quinazolinedione derivatives potentiated the anti-cancer effect of olaparib, a PARP-1 inhibitor, by inhibiting the growth of Capan-1 cells." (PMID 38203666, 2023). "At the same time, SIRT6 is considered as a suppressor and promotor of diverse diseases such as cancer, diabetes, and inflammation." (PMID 37630770, 2023). "SIRT6 plays a dual function in the development of cancer that can be connected to its ability to control different signaling pathways." (PMID 38203666, 2023). "Disturbances in SIRT6 expression levels have been observed in the development and progression of various types of cancer." (PMID 38203666, 2023). "Along with β-catenin, SIRT6 participates in a number of cellular signaling pathways, including those that contribute to cancer development." (PMID 38203666, 2023). "This suggests that SIRT6 plays a role in maintaining mitochondrial function and oxidative phosphorylation, which are typically suppressed in cancer cells." (PMID 38203666, 2023).